TRERF1 (transcriptional regulating factor 1)
Description:
Binds DNA and activates transcription of CYP11A1. Interaction with CREBBP and EP300 results in a synergistic transcriptional activation of CYP11A1.
Synonyms: BCAR2; RAPA; TREP132; TReP-132; HSA277276; dJ139D8.5
Tractability: PROTAC: ubiquitination databases record sites on it.
Gene: Protein-coding gene on chromosome 6 (42,224,931 to 42,452,224, reverse strand). Ensembl gene ENSG00000124496.
Subcellular location: Nucleus
Subcellular location (Human Protein Atlas): Nucleoplasm; Cytosol; Nucleoli fibrillar center
Gene Ontology:
Molecular function: nuclear progesterone receptor binding; protein binding; transcription coactivator activity; transcription coactivator binding; transcription corepressor activity
Biological process: cellular response to progesterone stimulus; positive regulation of DNA-templated transcription; positive regulation of transcription by RNA polymerase II; progesterone receptor signaling pathway; negative regulation of DNA-templated transcription; regulation of transcription by RNA polymerase II
Cellular component: nucleoplasm; nucleus; histone deacetylase complex; transcription regulator complex
Genetic constraint (gnomAD): Loss-of-function variants: 27 observed, 118.95 expected, observed/expected ratio (o/e) 0.23, 90% interval 0.17 to 0.31. The upper end of that interval is the gene's LOEUF score, 0.31, which puts it in group 1 of 6, group 1 being the genes least tolerant of losing a copy. Missense variants: 1,231 observed, 1,542.4 expected, observed/expected ratio (o/e) 0.8, 90% interval 0.76 to 0.84. Synonymous variants: 625 observed, 634.39 expected, observed/expected ratio (o/e) 0.99, 90% interval 0.92 to 1.05.
Homologues: Orthologues: chimpanzee TRERF1 (98% identical), macaque TRERF1 (98% identical), rabbit TRERF1 (92% identical), dog TRERF1 (91% identical), pig TRERF1 (90% identical), rat Trerf1 (90% identical), mouse Trerf1 (89% identical), guinea pig TRERF1 (82% identical), tropical clawed frog trerf1 (49% identical), Caenorhabditis elegans saeg-1 (16% identical), Caenorhabditis elegans Y105C5A.1 (10% identical), Caenorhabditis elegans spr-1 (7% identical), and 3 more. Paralogues in human: MIDEAS (24% identical), ZNF541 (23% identical), RCOR2 (7% identical), RCOR3 (7% identical), RCOR1 (6% identical).
Diseases named in the same sentence as TRERF1 in open-access papers:
TRERF1 is named in the same sentence as 23 diseases in open-access papers, as found by Europe PMC text mining. Sharing a sentence is not in itself a finding about the gene and the disease. The quoted sentences say what the papers report.
breast carcinoma (5 papers, 2014 to 2024). "TRERF1 gene encodes a basal cell cycle regulatory protein that has been shown to play a key role in development of estrogen independence/resistance in solid tumors—e.g., breast cancer." (PMID 31500094, 2019). "PCYT2 activity has been shown to be increased in breast cancer cells, enabling them to adapt to metabolic stress, and TRERF1 acts as a cell cycle inhibitor in breast cancer cells through the modulation of progesterone receptor." (PMID 26620706, 2015). "Particularly melanoma, carcinoma and solid tumors have the most significant enrichment of these genes, including ABCC11 (melanoma drug resistance), SNRNP200 (retinitis pigmentosa), TRERF1 (breast cancer) and WTX (Wilms tumor gene on X chromosome, Wilms tumor)." (PMID 25523808, 2014). "TRERF1 and MTUS1 are reported to be involved in the differentiation in breast cancer cells and oral tongue squamous cell carcinoma, respectively." (PMID 30171794, 2018).
depression (1 paper, 2024). "TRERF1 can possibly be associated with the response to electroconvulsive therapy in patients with major depressive disorder and plays a role in the mechanisms underlying some mental illnesses, including depression." (PMID 39640846, 2024).
ovarian carcinoma (1 paper, 2021). A malignant neoplasm originating from the surface ovarian epithelium. "In addition, several other potentially interesting targets of YTHDF2 in ovarian cancer have been identified, such as the putative tumor suppressors TRERF1, ZDHHC14, DIS3L, Vps18, NOD1, and SLC9A8." (PMID 33658012, 2021).
tumor (5 papers, 2015 to 2023). "Two additional TFs, TRERF1 and DLX1 were inferred to be more active in tumor than normal tissue." (PMID 37843125, 2023).
TRERF1 also shares sentences with these, for which no sentence is quoted: glioblastoma (2 papers); infection (2); melanoma (2); mental illnesses (2); Arthritis (1); bacterial infection (1); Baller-Gerold syndrome (1); carcinoma (1); cardiac hypertrophy (1); cervical cancer (1); cystitis (1); dystroglycanopathy (1); endometriosis (1); major depressive disorder (1); muscular atrophy (1); osteosarcoma (1); retinitis pigmentosa (1); tuberculosis (1); Wilms tumor (1).